GPC1 (glypican 1)
Diseases named in the same sentence as GPC1 in open-access papers (continued):
Sharing a sentence is not in itself a finding about the gene and the disease.
pancreatic cancer (continued). "Exosomal GPC-1 is not diagnostic for PDAC, whereas a group of microRNA in circulating exosomes is superior to exosomal glypican-1 levels for diagnosing pancreatic cancer." (PMID 31355137, 2019). "The best cut-off for the diagnosis of pancreatic cancer using the GPC1+GP2 EV test was greater than 780 EVs per microliter, yielding a sensitivity and specificity of 23.33% and 90.0% respectively." (PMID 30800217, 2019). "Several attempts recorded the successful identification of GPC1 (Glypican 1—a protein expressed on the surface of pancreatic cancer-derived exosomes) at an absolute sensitivity and specificity." (PMID 31212754, 2019). "Glypican-1 (GPC-1) was identified in June 2015 as a biomarker for early detection of pancreatic cancer, it was reported that the detection of GPC-1 was 100% correct for 250 patients." (PMID 30202003, 2018). "It is now essential to standardize methods for exosome isolation and crExos GPC1 quantification, in order to ultimately validate this biomarker as clinically relevant for patients with suspected pancreatic tumors." (PMID 29721179, 2018). "EVs with glypican-1 on their surface were previously identified as a biomarker for pancreatic cancer." (PMID 31162490, 2018). "Glypican-1 (GPC1) is a membrane-anchored protein overexpressed in BC and pancreatic cancer modulating mitogenic effects of various heparin-binding growth factors in these tumors." (PMID 29632535, 2018). "Melo and colleagues isolated pancreatic tumor-derived exosomes using a cell surface proteoglycan, glypican 1, which is specifically enriched on pancreatic cancer exosomes." (PMID 30380690, 2018). "One of these, GPC1, was found to increase in the blood of patients with breast and pancreatic cancer compared to controls, suggesting its use as a disease detection biomarker." (PMID 30071693, 2018). "Subsequently, Melo and colleagues identified glypican-1 (GPC-1) as a specific marker for pancreatic cancer." (PMID 29865250, 2018). "Yet another study reported the potential diagnostic use of glypican-1 (GPC1), a cell surface proteoglycan which was significantly elevated in exosomes of pancreatic cancer patients." (PMID 29616188, 2018). "Almost all miRNAs negatively regulate gene expression and GPC1 was upregulated in pancreatic cancer." (PMID 29245923, 2017). "Previous studies have observed that GPC1 is overexpressed in the tissues for pancreatic cancer, breast cancer, and glioma." (PMID 29254156, 2017). "In pancreatic cancer, miR‐96‐5p suppressed GPC1 expression 12, and miRNA‐149 is also thought to regulate GPC1 expression." (PMID 28233416, 2017). "GPC1+ crExos levels were significantly elevated in patients with histologically confirmed pancreatic cancer precursor lesions and PDAC compared with those in patients with benign pancreatic disease and healthy controls." (PMID 28440066, 2017). "The level of GPC1 positive exosomes is closely related to survival after surgery in patients with pancreatic cancer." (PMID 28233416, 2017). "We decided to use represented pancreatic cancer cell lines PK-8, PK-45H and BxPC-3 highly expressing GPC1." (PMID 29245923, 2017). "Circulating exosomes containing GPC1 (GPC1 + Exos) were isolated from blood of 250 pancreatic cancer patients, which helped to distinguish between chronic pancreatitis and pancreatic cancer patients (in early and terminal stages)." (PMID 28851367, 2017). "Glypican-1 positive exosomes were better at identifying early pancreatic cancer compared to CA19-9 when distinct changes in pancreatic histology were absent." (PMID 27999198, 2017). "Previous studies in pancreatic cancer have demonstrated that miR‐96‐5p suppressed GPC1 expression, thereby inhibiting the proliferation of pancreatic cancer cells, and high miR‐96‐5p expression is a predictive marker for good prognosis of pancreatic cancer." (PMID 28233416, 2017).
pancreatic cancer (continued). "Overexpression of GPC1 marks the full spectrum of human pancreatic cancer precursors and PDAC as a useful early marker of pancreatic neoplasms." (PMID 29245923, 2017). "The regulatory roles of miR-96-5p and miR-149 on GPC1 gene expression have been observed in pancreatic cancer and human endothelial cells." (PMID 29254156, 2017). "The relation between EVI1/miR-96 and GPC1 found in HPDE cell lines was further confirmed in pancreatic cancer cell lines." (PMID 29245923, 2017). "A recent study found that GPC1 positive exosomes are a highly specific and sensitive marker suitable for early diagnosis of pancreatic cancer." (PMID 29254156, 2017). "We examined the expression of GPC1 using real-time quantitative reverse transcription PCR (qRT-PCR) in 11 pancreatic cancer cell lines (BxPC-3, Capan-1, DANG, KLM-1, MIA PaCa-2, PANC-1, PK-1, PK-45H, PK-45P, PK-8, PK-9 cell lines) and HPDE cell lines." (PMID 29245923, 2017). "In PDACs, about 50% of cases demonstrated GPC1 expression in the stromal cells surrounding the pancreatic cancers." (PMID 29245923, 2017). "In these pancreatic cancer cell lines, downregulation of GPC1 by siRNA significantly suppressed cell proliferation and inhibited cell migration." (PMID 29245923, 2017). "Currently, based on ultracentrifugation method, glypican 1, PSA has been respectively identified as early diagnostic biomarkers in pancreatic cancer and prostate cancer in blood exosomes." (PMID 29282096, 2017). "The most impressive finding with GPC1 is the diagnosis of the early stage of pancreatic cancer from other benign pancreatic diseases, with 100% sensitivity and specificity." (PMID 27673558, 2016). "In other types of cancer such as pancreatic cancer, exosomal biomarker, Glypican-1, has already demonstrated ability to distinguish between healthy controls and advanced cancer patients with 100% accuracy." (PMID 27191983, 2016). "Recent studies indicate the specific association of some proteins such as MET in the case of melanoma, and glypican-1 in the case of pancreatic cancer with exosomes, and their role in promoting the malignant transformation." (PMID 27086912, 2016). "Recently, an assay was developed to detect a proteoglycan molecule, glypican-1 (GPC1) found on extracellular vesicles in patients with late-stage pancreatic cancer with 100% confidence." (PMID 27092178, 2016). "Glypican 1 expression is upregulated in pancreatic cancer cells and surrounding fibroblasts, and the mitogenic response of pancreatic cancer cells to bFGF and HB-epidermal growth factor is abrogated by antisense attenuation of this HS-PG." (PMID 26448753, 2015). "We have recently demonstrated that glypican-1 protein on the surface of tumour-derived exosomes can be used as a biomarker for the early detection of pancreatic cancer." (PMID 26316886, 2015). "GPC1 crExos were detected in the serum of patients with pancreatic cancer with absolute specificity and sensitivity, distinguishing healthy subjects and patients with a benign pancreatic disease from patients with early- and late-stage pancreatic cancer." (PMID 26316886, 2015). "Few studies have also showed that distortion in the expression levels of yet another glypican family GPC1, leads to cervical and pancreatic cancers." (PMID 26583080, 2015). "To determine the relationships between miR-96-5p/-182-5p and GPC1 in pancreatic cancer (PC), we conducted the population and in vitro studies." (PMID 24736782, 2014). "We followed 38 pancreatic cancer patients, measured and compared the expression of miR-96-5p/-182-5p, GPC1, characteristics and patients’ survival time of different miR-96-5p/-182-5p expression levels in PC tissues." (PMID 24736782, 2014). "The heparan sulfate proteoglycan, Glypican-1 (GPC1), significantly impacts the growth of pancreatic cancer cells in vivo and markedly attenuates tumor angiogenesis and metastasis in athymic mice." (PMID 19082421, 2008).
pancreatic cancer (continued). "Since HSPGs such as glypican-1 play an important role in pancreatic cancer and since Hsulf-1 can influence the sulfation state and the biological function of HSPGs, the expression and functional role of Hsulf-1 was analyzed in pancreatic cancer." (PMID 15817123, 2005). "One member of the HSPG family, glypican-1 is over-expressed in pancreatic cancer and influences heparin binding growth factor signaling in this disease." (PMID 15817123, 2005). "Moreover, exosomes from pancreatic cancer patients overexpressed Glypican-1 (GPC1), suggesting its potential as a biomarker for pancreatic cancer diagnosis and stratification." (PMID 40530018, 2025). "Similarly, pancreatic cancer detection has been enhanced through GPC1-enriched exosomes, demonstrating exceptional sensitivity and specificity for early-stage diagnosis." (PMID 40149276, 2025). "Additionally, exosomal biomarkers such as glypican-1 (GPC1) show 97.3% sensitivity in pancreatic cancers, with potential applications in small intestinal malignancies." (PMID 40227568, 2025). "This pattern is consistent with previous reports in the literature, where GPC1 membrane protein was found to be highly expressed on the tMV surface in pancreatic cancers, and plasma membrane receptors such as EGFR and EGFRvIII were upregulated in the MV fractions from cancer cells in glioma tumors." (PMID 40285610, 2025). "Three cancer‐correlated biomarkers (epidermal growth factor receptor (EGFR), one pancreatic cancer marker (glypican‐1, GPC1) and macrophage migration inhibitory factor (MIF)) can be detected by the developed MAIP‐based platform with a detection limit as low as 5 pg mL−1." (PMID 40598854, 2025). "Interestingly, a related glypican protein known as glypican-1 (GPC1) has recently shown promise in the literature as a biomarker in pancreatic cancer." (PMID 39598037, 2024). "It has been proposed that GPC1-positive exosomes are highly expressed in the sera of pancreatic cancer patients and the exosomal protein GPC1 (AUC= 1.0) yields significantly better performance than CA19–9 (AUC = 0.739) in differentiating pancreatic cancer patients from healthy controls." (PMID 38983854, 2024). "GPC1+ crExos demonstrated 100% sensitivity and specificity across all pancreatic cancer stages (in situ, stage I, and stages II–IV), highlighting their potential as biomarkers throughout the progression of pancreatic cancer and their application in early detection." (PMID 39596226, 2024). "GPC1 may ultimately prove to be a more fruitful area for future pancreatic cancer research than GPC3." (PMID 39598037, 2024). "As early as 2015, studies showed that glypican-1 is specifically enriched in EVs derived from cancer cells, so GPC1 circulating EVs can be used as a potential non-invasive diagnostic and screening tool for early pancreatic cancer." (PMID 38542448, 2024). "As the 5-year survival rate of patients with pancreatic cancer receiving the standard therapies is poor (9%), GPC1-targeting ADCs might represent attractive therapeutic candidates." (PMID 39065798, 2024). "Our attention has been drawn to the various expression levels of GPC1 in pancreatic cancer." (PMID 37031249, 2023). "In 2015, Dr. Raghu Kallur’s team found that GPC1 protein contained in exosomes of pancreatic cancer cells could be used as a non-invasive method to diagnose and screen early pancreatic cancer at a stage suitable for surgical treatment." (PMID 37349803, 2023). "Previous studies identified soluble GPC1 in pancreatic tumor cell-derived exosomes." (PMID 37031249, 2023). "Moreover, recent clinical studies have identified GPC1 as a novel prognostic biomarker in patients with advanced pancreatic cancer and pancreatic ductal adenocarcinoma." (PMID 36944188, 2023). "For example, the proteoglycan glypican-1 positive (GPC1+) exosomes derived from the serum of pancreas cancer patients could distinguish early- and late-stage pancreas cancer as well as patients with a benign pancreas disease." (PMID 36770959, 2023).
pancreatic cancer (continued). "GPC-1 has become a controversial biomarker in pancreatic cancer." (PMID 37880707, 2023). "Experimental studies link GPC1 to several types of cancers including pancreatic cancer, breast cancer, glioblastoma, esophageal squamous cell carcinoma (ESCC), colorectal cancer, mesothelioma, prostate cancer, hepatocellular carcinoma and cervical cancer as few examples among many published studies." (PMID 36944188, 2023). "GPC1 is also expressed on FAP-positive CAFs in pancreatic cancer." (PMID 35159011, 2022). "Thus, GPC1+Exos can be utilized to diagnose early and advanced pancreatic cancer with high precision and sensitivity, as well as evaluate treatment." (PMID 36407096, 2022). "Some studies have reported that GPC-1 is highly expressed in multiple human cancer tissues, such as pancreatic cancer, breast cancer, glioblastoma, and ESCC, and overexpression of GPC-1 in tumor tissues was found to be associated with shorter OS in patients with PC, ESCC, breast cancer, and glioma." (PMID 36313694, 2022). "GPC1+ EVs could also be used as a prognostic marker for patients with advanced pancreatic cancer receiving regional intra-arterial chemotherapy treatment." (PMID 35501802, 2022). "GPC1 expression level in serum of pancreatic ductal adenocarcinoma was 100% specific and sensitive for the diagnosis of early pancreatic cancer, and it is an ideal marker for early pancreatic cancer." (PMID 36110946, 2022). "Following this observation, GPC1 in PDAC exosomes could be used as a highly specific biomarker for pancreatic cancer." (PMID 35501802, 2022). "Glypican-1 (GPC1)-positive exosomes could be used as an early diagnosis tool for patients with pancreatic cancers, which also performed better in prognosis prediction compared with CA19-9." (PMID 35255950, 2022). "GPC1 alone has an 82% sensitivity and 52% specificity for pancreatic cancer screening." (PMID 35159011, 2022). "Compared with healthy subjects, glypican-1 (GPC-1) was found to significantly increase in serum exosome of patients with pancreatic cancer and could be used for the early detection of pancreatic cancer with 100% diagnostic specificity and sensitivity." (PMID 35180868, 2022). "Similarly, in colorectal Cancer, the cell surface proteoglycan Glyptican1 (GPC1) serves as the most prominent biomarker of pancreatic cancer." (PMID 36032679, 2022). "Decreased GPC1 expression suppresses pancreatic cancer cell growth by modifying TGF-β signaling." (PMID 35671267, 2022). "Modulation of p-ERK 1/2 protein levels by GPC-1 has been previously seen in the literature where attenuation of GPC-1 expression is observed with the concomitant reduction in p-ERK 1/2 activation in pancreatic cancer cells." (PMID 33927256, 2021). "Furthermore, we demonstrate the successful application in discriminating pancreatic cancer cells by analyzing EVs’ GPC1 mRNA expression levels." (PMID 34565398, 2021). "Glypican-1 (GPC1) has been considered a pancreatic tumor marker for more than 20 years." (PMID 34249755, 2021). "One study reported that circulating EVs that were glypican-1–positive could be used as biomarkers for early detection and prognosis in patients with pancreatic cancer." (PMID 33592500, 2021). "In a study on the exosomes of pancreatic cancer patients (n=6), GPC1 was not diagnostic and its levels remained unvaried 24h after surgical resection." (PMID 34249755, 2021). "GPC-1 is an important clinical biomarker involved in the process of cancer onset, and it can be used as an important indicator of disease prognoses, such as breast cancer, lung cancer, colorectal cancer, glioma, pancreatic cancer, and esophageal cancer." (PMID 33902495, 2021). "In contrast, other studies have failed to confirm the diagnostic value of GPC1 alone in pancreatic cancer, highlighting the need for the combination of GPC1 with other biomarkers to increase diagnosis accuracy." (PMID 33791224, 2021).
pancreatic cancer (continued). "Circulating exosomes with overexpressed glypican 1 (GPC1) in the serum of patients closely correlate with pancreatic cancer, which could be used as a highly specific biomarker for pancreatic cancer." (PMID 34234872, 2021). "Two important examples are GPC1 in pancreatic cancer and SDC1 in glioma." (PMID 33494442, 2021). "It has been reported that GPC1 has a higher specificity for pancreatic cancer than CA19-9." (PMID 34527051, 2021). "One was based on the detection of pancreatic cancer EV biomarker ephrin type-A receptor 2, while the other obtained a high sensitivity and specificity with the combination of 5 EV markers (one of them being Glypican-1)." (PMID 34360924, 2021). "Qian and colleagues took advantage of the presence of Glypican-1 (GPC1) in extracellular vesicles (EVs) to determine if the change in GPC1+ cells in EVs could be a predictor of the consequences of RIAC for advanced pancreatic cancer patients." (PMID 33672926, 2021). "Proteoglycans especially glypican-1 (GPC1), which enriched on cancer-cell-derived exosomes, may play a role as a biomarker to detect early stages of pancreatic cancer." (PMID 32583064, 2021). "GPC1 is specifically enriched in pancreatic patient serum-derived exosomes, distinguishing chronic patients and healthy people from patients with early- or late-stage pancreatic cancer." (PMID 33613112, 2021). "The amount of EVs related GPC1 mRNA expression level could relate to the periods of pancreatic cancer." (PMID 34565398, 2021). "It was shown earlier that GPC1 accumulates in pancreatic cancer cell-derived exosomes." (PMID 32629890, 2020). "Of further importance, GPC1 has also been found to be enriched in cellular exosomes from cancer types ranging from pancreatic to colorectal cancer, and has been investigated as a potential biomarker for the early detection of pancreatic cancer." (PMID 32017809, 2020). "In addition, glypican-1(GPC1) in serum EVs is significantly increased in patients with pancreatic cancer, and even in patients with precancerous lesions, suggesting the great potential of GPC1 in EVs for the early diagnosis of pancreatic cancer." (PMID 33169793, 2020). "Analysis of Glypican-1 positive EV in circulation distinguishes with absolute specificity and sensitivity healthy subjects and patients with a benign pancreatic disease from patients with early- and late-stage pancreatic cancer and non-pancreatic cancer." (PMID 33062295, 2020). "This discrepancy may account for the observed differences in GPC-1-ADC antitumour efficacy among the pancreatic cancer cell lines." (PMID 32152502, 2020). "Moreover, by analyzing their content researchers have for instance found that exosomal glypican-1 (GPC1) protein distinguished patients with pancreatic cancer with absolute specificity and sensitivity from healthy subjects." (PMID 37361495, 2020). "Recently, a milestone study has shown that glypican-1 (GPC1) positive exosomes were detectable in the serum of patients with pancreatic cancer with a high level of specificity and sensitivity, as compared to both healthy subjects and patients with a benign pancreatic disease." (PMID 32916840, 2020). "In addition to PCa, overexpression of GPC-1 has been described in a range of solid tumours, including glioblastoma, pancreatic cancer, oesophageal, bladder, breast, ovarian, cervical and mesothelioma." (PMID 32382920, 2020). "Flow cytometry was performed to measure GPC-1 protein on pancreatic cancer cell surfaces." (PMID 32152502, 2020). "First, GPC-1 expression was heterogeneous in clinical pancreatic cancer." (PMID 32152502, 2020). "Detection of GPC1+ circulating TEXs in the serum of patients with pancreatic cancer distinguished healthy donors and patients with a benign pancreatic disease from patients with early- and late-stage pancreatic cancer with high sensitivity and specificity." (PMID 31438991, 2019).